MCL1 (MCL1 apoptosis regulator, BCL2 family member)
Diseases named in the same sentence as MCL1 in open-access papers (continued):
Sharing a sentence is not in itself a finding about the gene and the disease.
malignant glioma (6 papers, 2013 to 2025). A grade III or grade IV glioma arising from the central nervous system. "ATF5 then activates the transcription of the anti-apoptotic gene myeloid cell leukemia sequence 1 (MCL1) transcription by binding its promoter and increasing the malignant glioma survival through the CREB3L2/ATF5/MCL1 anti-apoptotic pathway." (PMID 35806136, 2022). "In terms of MCL-1 acting as a rational drug treatment therapeutic target, a genome-wide RNA interference screen identified MCL-1 as a key downstream survival factor in malignant glioma for therapeutic implications." (PMID 34384473, 2021).
prostate tumors (6 papers, 2008 to 2022). "MiR-29b is expressed at low levels in prostatic tumor tissues and, when upregulated, inhibits Mcl-1, matrix metalloproteinase-2 (MMP-2), and collagen." (PMID 35898539, 2022). "This highlights the need for further investigation to determine whether MCL‐1 is a critical target in AR‐v7 expressing prostate tumors." (PMID 31228231, 2019). "Of note, in prostate tumor treated with Docetaxel and ABT263, the remaining senescent tumor cells upregulated MCL-1 and genes related to angiogenesis, cell migration and wound healing." (PMID 35449130, 2022). "Both BAD and MCL-1 are ubiquitously expressed in prostate tumors and could be dynamically regulated by phosphorylation (in the case of BAD) and both phosphorylation and ubiquitylation (in the case of MCL-1)." (PMID 24040284, 2013).
Sepsis (6 papers, 2012 to 2024). Sepsis is defined as life-threatening organ dysfunction caused by a dysregulated host response to infection. "A relationship between decreased Mcl-1 mRNA expression and an increase in neutrophil apoptosis has previously been reported for patients with sepsis, but until now, research on COPD patients has been lacking." (PMID 22686245, 2012). "However, when challenged with known mediators of sepsis, human neutrophils of healthy donors or neutrophils from patients with sepsis exhibited impaired MNDA relocation/cleavage parallel with myeloid cell leukemia-1 (MCL-1) accumulation and suppression of apoptosis." (PMID 23293639, 2012). "Mcl-1 and Bcl-2 can prevent Fas-mediated PMN apoptosis and both are upregulated in PMN from patients with sepsis." (PMID 33262756, 2020).
T-cell acute lymphoblastic leukemia (6 papers, 2019 to 2025). Acute lymphoblastic leukemia of T-cell origin. "FBW7 regulates cellular apoptosis by targeting Mcl1 for ubiquitination and destruction and plays important roles in T-cell acute lymphoblastic leukemia." (PMID 38485719, 2024). "Current research has documented that in T-cell acute lymphoblastic leukemia, FBXW7 deletion results in the upregulation of MCL1, thereby conferring resistance to the BCL2 inhibitor ABT737." (PMID 40169588, 2025). "In patients with T-cell ALL (T-ALL), JDP2 promoted cell survival by upregulating anti-apoptotic myeloid cell leukemia-1 (MCL1) protein." (PMID 40765830, 2025).
Alzheimer disease (5 papers, 2019 to 2023). A progressive, neurodegenerative disease characterized by loss of function and death of nerve cells in several areas of the brain leading to loss of cognitive function such as memory and language. "Our findings shed light on the mechanisms of mitophagy, reveal that MCL-1 is a mitophagy receptor that can be targeted to induce mitophagy, and identify MCL-1 as a drug target for therapeutic intervention in Alzheimer’s disease." (PMID 33184293, 2020). "The role of MCL-1 in mitophagy and mitochondrial function may allow MCL-1 to be used therapeutically to target neurodegenerative diseases, including Alzheimer’s disease." (PMID 37601693, 2023). "In previous studies, our research methods have been widely used, such as the screening of CD13 natural inhibitors, bacopa monnieri in the treatment of Alzheimer’s Disease, novel inhibitors against β-lactamase CTX-m-152, MCL-1 inhibitors, etc., using the same or similar research methods as ours." (PMID 35603567, 2022).
Autoimmunity (5 papers, 2015 to 2024). The occurrence of an immune reaction against the organism's own cells or tissues. "Its complete deletion in MCL-1 depleted cells has recently been found to completely rescue a lethal multiorgan autoimmunity, supporting a key role in the control of immune tolerance." (PMID 35205739, 2022). "Another member of the Bcl-2 protein family, Mcl-1, was shown to play a key role in hematological and biliary malignancies as well as in fatal autoimmune disorders." (PMID 26246474, 2015). "However, Treg-specific deletion of Mcl-1 produced lethal autoimmunity as early as 4 weeks of age, a much shorter time frame than the potential role we detected for Bcl-2 in supporting IL-2-dependent Treg survival." (PMID 30833563, 2019). "Thus, Bcl-2 protein, a member of the Bcl-2 family (Bcl-2, Bcl-xL, Bax, Mcl-1) that serves as a main barrier against autoimmune disorders, modulates calcium signaling via mtCU potentiation." (PMID 26246474, 2015). "Mice having Treg-specific deletion of Mcl-1 lose Treg cells resulting in autoimmunity." (PMID 26009874, 2015). "Indeed, BCL-2 is not required for Treg survival, as opposed to MCL-1, another member of the BCL-2 pathway, the loss of which leads to fatal autoimmunity in a mouse model." (PMID 38812504, 2024).
chlamydial infection (5 papers, 2008 to 2025). "To elucidate the upstream signals responsible for Mcl-1 stabilization during chlamydial infection, we analyzed the associated signaling pathways." (PMID 41051248, 2025). "We deleted Mcl-1 in HeLa cells, the most commonly used cell for chlamydial infection." (PMID 35397654, 2022). "As C. trachomatis infection predominantly blocks apoptosis upstream of mitochondrial outer membrane permeabilization and cytochrome c release, we checked if interfering with Mcl-1 expression could sensitize Chlamydia infected cells to apoptosis." (PMID 18769617, 2008).
Clear Cell Renal Cell Carcinoma (5 papers, 2014 to 2024). "We observed that clear cell renal cancer (ccRCC) cell lines with damaging PBRM1 mutations displayed a strong dependency on MCL1." (PMID 38371625, 2024). "Our analysis revealed that clear cell Renal Cell Carcinoma (ccRCC) cell lines with deleterious alterations in the PBRM1 (Polybromo 1) gene displayed a strong dependency on MCL1." (PMID 38371625, 2024). "There is only a single report analyzing Mcl-1 isoforms & their clinical significance so far in clear cell renal carcinomas." (PMID 25409302, 2014). "PVT1 may thus serve as a novel biomarker, and the PVT1/Mcl-1 pathway may be a useful therapeutic target for clear cell renal cell carcinoma." (PMID 29254209, 2017). "To determine the functional importance of c-FLIP (L) and Mcl-1 (L) in KMU-191-mediated apoptosis, we used human clear cell renal cell carcinoma Caki cells engineered to overexpress c-FLIP (L) and Mcl-1 (L)." (PMID 37576393, 2023).
colitis (5 papers, 2017 to 2023). Inflammation of the colon. "In support of our findings, Liu and colleagues showed that MCL-1 is down-regulated in intestinal tissues from patients with ulcerative colitis and mice with dextran sodium sulfate-induced colitis." (PMID 28190086, 2017). "miR-29a promoted apoptosis of intestinal epithelial cells in colitis by downregulating MCL-1." (PMID 36743692, 2023). "Moreover, they showed that miR-29a targeted the 3′UTR of the Mcl-1 gene and downregulated the expression of Mcl-1 in colonic tissues in the experimental murine model of colitis as well as in UC patients." (PMID 34831425, 2021).
gastric adenocarcinoma (5 papers, 2016 to 2022). "Of these, 8 regions contained previously characterized amplified oncogenes: GATA4, CCND1, CDK6, MDM2, EGFR, MCL1, ERBB3 and MYB; this is the first report of significant and nearly isolated MYB amplification in gastric adenocarcinoma." (PMID 28426752, 2017).
liver fibrosis (5 papers, 2017 to 2025). "We next examined the effect of hepatocyte Mcl1 deficiency on the FFC diet-induced liver fibrosis." (PMID 32015322, 2020). "Conversely, overexpression of MCL1 in the liver protected against the pro-apoptotic effects of FBXO2+ SMEV treatment, further confirming the role of MCL1 in FBXO2+ SMEV-mediated hepatic fibrosis." (PMID 40852599, 2025). "Additionally, the overexpression of the Mcl-1 minigene in humans leads to apoptosis resistance by promoting liver damage resulting in liver fibrosis." (PMID 39188653, 2024). "On the other hand, the overexpression of Mcl-1 leads to apoptosis resistance and consequently results in liver damage and the development of hepatic fibrosis, due to the involvement of BOK in hepatocarcinogenesis in mice models when diethylnitrosamine (DEN) was used." (PMID 39188653, 2024). "Myeloid cell leukemia-1 (MCL-1), a member of the B-cell CLL/Lymphoma 2 (BCL-2) apoptosis family, is involved in liver fibrosis and is targeted by miR-29b via its 3’-UTR in cultured cell lines." (PMID 28190086, 2017).
myocardial infarction (5 papers, 2015 to 2024). Gross necrosis of the myocardium, as a result of interruption of the blood supply to the area, as in coronary thrombosis. "Our pull-down data suggest that this role is particularly important in disease states that rely on elevated MCL1 (e.g., post–spinal cord injury, post–myocardial infarction, cancers)." (PMID 37142223, 2023). "In contrast, Mcl-1 did not inhibit activation of autophagy during myocardial infarction or mitochondrial depolarization." (PMID 35563775, 2022). "The finding that Mcl-1 failed to inhibit autophagy in response to myocardial infarction and FCCP treatment prompted us to investigate the effect of Mcl-1 on mitochondrial clearance." (PMID 35563775, 2022).
pancreatic ductal adenocarcinoma (5 papers, 2016 to 2025). An infiltrating adenocarcinoma that arises from the epithelial cells of the pancreas. "We recently found that the high expression of the mesenchymal FGFR2c variant in human pancreatic ductal adenocarcinoma (PDAC)-derived cells triggers the PKCε-mediated improvement of EMT and of MCL-1/SRC-dependent cell invasion." (PMID 38339360, 2024).
papillary thyroid carcinoma (5 papers, 2015 to 2024). "In papillary thyroid cancer cell lines, OB3 and leptin reduced the expression of PCNA and MCL1 in BHP18-21, however, only leptin reduced the expression of PCNA and c-Myc in BHP2-7 cells." (PMID 27050378, 2016).
pneumococcal infection (5 papers, 2008 to 2023). Infections with bacteria of the species streptococcus pneumoniae. "Following pneumococcal infection, Huwe1 promotes macrophage apoptosis by ubiquitinating the anti-apoptotic protein Mcl-1 and therefore targeting it for degradation by the proteasome." (PMID 37033482, 2023). "Various studies have established that Mcl-1 mRNA is up-regulated as part of an early rapid cellular response to cytotoxic stimuli such as calcium ionophores, chemotherapeutic agents, pneumococcal infection and UV irradiation." (PMID 31763216, 2019). "Some studies have demonstrated that Mcl-1 mRNA is up-regulated as part of an initial rapid cellular response to cytotoxic stimuli such as chemotherapeutic agents, calcium ionophores, pneumococcal infection and UV irradiation." (PMID 25587328, 2014). "In this study, we demonstrate that LMP and cathepsin D activation trigger macrophage apoptosis via Mcl-1 downregulation during pneumococcal infection." (PMID 21298030, 2011). "The enhancement of the Mcl-1-Mule interaction, which was triggered by pneumococcal infection, was demonstrated by immunoprecipitation of either Mcl-1 or Mule and was reversed by pepstatin A." (PMID 21298030, 2011). "We have previously shown that the mitochondrial apoptosis pathway is only activated when Mcl-1 expression in macrophages falls below maximal levels during pneumococcal infection." (PMID 21298030, 2011). "During pneumococcal infection Mcl-1 downregulation is regulated post-transcriptionally with evidence of enhanced ubiquitination." (PMID 21298030, 2011). "In contrast, we observed that pneumococcal infection enhanced the ubiquitination of Mcl-1 and that cathepsin D inhibition reversed this process." (PMID 21298030, 2011). "Pepstatin A treatment also reduced the loss of Mcl-1 following pneumococcal infection in MDMs (data not shown)." (PMID 21298030, 2011). "The essential role of Mcl-1 in regulating cell viability has been established in various experimental settings, including a murine host-mediated macrophage apoptosis model during pneumococcal infection." (PMID 18211685, 2008).
Arthritis (4 papers, 2013 to 2025). Inflammation of a joint. "Further investigation of the relationship between both clinical and bacteriological signs of arthritis and Mcl-1 expression in joints revealed the significant association." (PMID 23431241, 2013). "Finally, we confirmed our observation in vivo in murine model of septic arthritis showing the association between the severity of arthritis and Mcl-1 expression." (PMID 23431241, 2013). "Specific MCL‐1 inhibitors show promising potential in arthritis models due to their role in promoting neutrophil apoptosis." (PMID 38044275, 2024). "MCL1 is another biomarker that plays a vital role in the arthritis joints." (PMID 34670585, 2021).
autoimmune disease (4 papers, 2015 to 2023). A disorder resulting from loss of function or tissue destruction of an organ or multiple organs, arising from humoral or cellular immune responses of the individual to their own tissue constituents. "However, the effect of Mcl-1 inhibition in inducing cell death was most prominent in both CD4+/CD8+ T cells of healthy controls compared to autoimmune diseases." (PMID 37993903, 2023). "Recently we reported the involvement of Notch signaling and its downstream impact on IL-6 and MCL-1 in macrophages immune response and defense mechanisms against MAP infection, the bacteria that have been associated with many autoimmune diseases like RA and CD." (PMID 34025650, 2021).
basal cell carcinoma (4 papers, 2019 to 2024). A carcinoma involving the basal cells. "In addition, the overexpression of IL-6 induced Mcl-1 overexpression and inhibited apoptosis in basal cell carcinoma." (PMID 39272918, 2024).
brain tumors (4 papers, 2016 to 2024). "In these brain tumors miR-181a was shown to target the anti-apoptotic genes BCL2 and MCL1, and downregulated miR-181a reduced glucose deprivation-induced apoptosis and caused mitochondrial dysfunction in astrocytes." (PMID 27517749, 2016).
Chlamydia infection (4 papers, 2015 to 2025). "We found mostly distinct patterns of gene expression (Mcl1 and cIAPs) elicited by each pathogen-host pair indicating Chlamydiae infection across host species boundaries does not induce a universally shared host response." (PMID 26779446, 2015).
dilated cardiomyopathy (4 papers, 2015 to 2024). Cardiomyopathy which is characterized by dilation and contractile dysfunction of the left and right ventricles. "Conversely, cardiac-specific ablation of Mcl1 results in a rapidly fatal, dilated cardiomyopathy manifested by loss of abnormal myocyte structure." (PMID 33469534, 2020). "Previous studies have found that cardiomyocyte-specific Mcl-1 knockout mice lead to rapid dilated cardiomyopathy and death." (PMID 35126811, 2022). "Using Mcl-1 conditional knocked-out mice, Opferman’s group found that cardiac-specific ablation of Mcl-1 in cardiomyocytes resulted in a rapidly fatal dilated cardiomyopathy, which suggested that pharmacological Mcl-1 inhibition might result in an unexpected cardiotoxicity." (PMID 39372954, 2024).
Ewing sarcoma (4 papers, 2011 to 2022). A small round cell tumor that lacks morphologic, immunohistochemical, and electron microscopic evidence of neuroectodermal differentiation. "We identified differential sensitivities of Ewing sarcoma cells to BCL-2 family inhibitors dependent on the EWS-FLI1 regulome including altered MCL-1 expression and subcellular localization." (PMID 30123424, 2018). "TT strongly upregulated the PMAIP1 pro-apoptotic protein in both Ewing sarcoma cell lines, but didn't affect MCL1 expression resulting in less effective apoptosis induction." (PMID 27589063, 2016). "Here we demonstrate that reconstituting the aqueous and triterpene components from mistletoe in the viscumTT extract synergistically induces caspase-dependent apoptosis associated with CLSPN, MCL1, BIRC5 and XIAP downregulation in Ewing sarcoma cell lines in vitro and primary cells ex vivo." (PMID 27589063, 2016).
gastric tumor (4 papers, 2020 to 2023). "With this approach we identified MDM2 ligase, coupled with inhibitors of the targets BCL2L1, BRD4, CDK9, PLK1 and MCL1 in stomach tumor tissue, as a therapeutic strategy." (PMID 35249548, 2022).
kidney cancer (4 papers, 2014 to 2023). Primary or metastatic malignant neoplasm involving the kidney. "In contrast to the active MCL-1 studies in the cancer field, limited studies on MCL-1 are available in renal/kidney cancer." (PMID 34384473, 2021). "FBW7-deficient human T-ALL cell lines were more sensitive to sorafenib (a drug approved for the treatment of primary kidney cancer) via regulation of MCL1 degradation." (PMID 24457827, 2014).